SPP1 (secreted phosphoprotein 1)
Diseases named in the same sentence as SPP1 in open-access papers (continued):
Sharing a sentence is not in itself a finding about the gene and the disease.
glioblastoma (67 papers, 2000 to 2026). The most malignant astrocytic tumor (WHO grade IV). "The upregulation of secreted phosphoprotein 1 (Spp1), a glycophosphoprotein expressed in immune cells like BMDMs and T cells that is responsible for chemotaxis and migration, has been reported in glioblastoma cells." (PMID 40361384, 2025). "Previous research has also demonstrated the significance of SPP1 as a chemokine in recruiting macrophages to glioblastomas, facilitating communication between tumor cells and the innate immune system, and potentially serving as a therapeutic target." (PMID 38329443, 2024). "Osteopontin (SPP1) a protein that, among other things, is involved in merlin/schwannomin degradation and in enhancing glioblastoma aggressiveness was also present in cystic fluid collected from CS and CG." (PMID 37627098, 2023). "Transcription of the SPP1 (OPN) gene is also regulated by miR-181a both in glioblastoma as well as during aging." (PMID 37444590, 2023). "Osteopontin (OPN/SPP1) also plays a vital role in recruiting macrophages to glioblastoma, regulating cellular communication between tumor cells and the TAMs via integrin αvβ5 on the glioblastoma-infiltrating macrophages." (PMID 37012233, 2023). "The levels of GLI1 and OCT4 mRNAs were determined in the same samples of normal brain, pilocytic astrocytomas and glioblastomas analyzed for SPP1 expression." (PMID 28030801, 2017). "In glioblastoma, SPP1 was found to be responsible for neutrophil and macrophage infiltration." (PMID 36959981, 2023). "Elevated expression of GPNMB (glycoprotein non-metastatic B) and SPP1 in microglia is linked to an unfavorable prognosis in glioblastoma patients." (PMID 37700840, 2023). "GBM and glioblastoma stem cells (GSCs) use Spp1 to recruit macrophages into the TME." (PMID 36555253, 2022). "T98G and LN18 glioblastoma cells had lower levels of SPP1 mRNAs than astrocytes." (PMID 28030801, 2017). "HSPA7 was found to promote macrophage infiltration and SPP1 expression by upregulating YAP1 and LOX in glioblastoma stem cells (GSCs), both in vitro and in clinical GBM tumor samples." (PMID 39199429, 2024). "We confirmed that HSPA7 promoted macrophage infiltration and SPP1 expression via upregulating the YAP1 and LOX expression of glioblastoma stem cells (GSCs) in vitro and in our clinical GBM tumor samples." (PMID 34354698, 2021). "SPP1 (OPN) is a ligand of CD44 that is secreted by both myeloid and glioblastoma cells." (PMID 40191733, 2025). "For example, RGCC, SPP1 (osteopontin), GPNMB, and APOE are highly expressed in hepatocellular carcinoma (HCC), whereas PLVAP (PV1), CD276 (B7-H3), and ESM1 are predominantly expressed in glioblastoma (GBM)." (PMID 41303611, 2025). "In total mRNA expression of TIMP-1, ANGPT1, SPP1, TGF-β1 and YKL-40 genes was analysed in 61 patients with different grade astrocytoma: 20 grade II diffuse astrocytoma, and 41 grade IV astrocytoma (glioblastoma), and in case of IP-10—in 11 grade II diffuse astrocytoma, and 24 glioblastoma samples." (PMID 34162919, 2021).
pancreatic cancer (67 papers, 2009 to 2026). "RESULTS: SPP1 was highly expressed in pancreatic cancer and associated with poor prognosis, elevated immunosuppressive microenvironment scores, and increased M2 macrophage infiltration." (PMID 41731467, 2026). "The presence of SPP1+ macrophages is associated with poor prognosis, and this has been identified in colorectal and pancreatic cancer." (PMID 40362553, 2025). "Similar roles for the SPP1-CD44 axis have been observed in other cancers, such as pancreatic cancer, where SPP1 secreted by cancer-associated fibroblasts (CAFs) enhances stem cell characteristics through CD44 interaction." (PMID 40076844, 2025). "Whittle and colleagues reported that Runx3 regulates a notable number of genes implicated in ECM functions, including Col6a1 and Spp1, to directly stimulate cell migration and dissemination and thereby promote metastasis in pancreatic cancer." (PMID 38240752, 2024). "Higher SPP1 expression has previously been associated with poor prognosis in breast and pancreatic cancer." (PMID 37505292, 2023). "Knockdown of SPP1 greatly decreased stemness features in cancer-associated fibroblasts treated with pancreatic cancer cells." (PMID 37287976, 2023). "To determine whether cerivastatin treatment affects invasiveness of pancreatic cancer cells, we assessed selected markers previously reported to be associated with metastatic processes in pancreatic cancer, i.e. SPP1 and SOX2." (PMID 27175805, 2016). "METHODS: Bioinformatics analyses were performed using TCGA and CCLE databases to assess SPP1 expression, prognostic value, and immune correlations in pan-cancer and pancreatic cancer." (PMID 41731467, 2026). "OBJECTIVE: To investigate the expression pattern of SPP1 in pancreatic cancer and its role in the tumor immune microenvironment, with functional validation by in vivo and in vitro experiments." (PMID 41731467, 2026). "CONCLUSION: SPP1 plays a critical role in regulating macrophage polarization and shaping an immunosuppressive tumor microenvironment in pancreatic cancer, suggesting its potential as a therapeutic target." (PMID 41731467, 2026). "In the microenvironment of pancreatic cancer tumors, interactions between endoprosthetic cells and T cells occur through the MK signaling pathway, SPP1 signaling pathway, and GALECTIN signaling pathway." (PMID 40487760, 2025). "The result showed that pancreatic cancer patients with a high proportion of SPP1+ macrophages had a significantly shorter survival, indicating the important role of SPP1+ macrophages in pancreatic cancer progression and patient prognosis." (PMID 41176774, 2025). "For instance, in pancreatic cancer, elevated SPP1 expression has been correlated with improved patient prognosis." (PMID 41391064, 2025). "SPP1 has recently been identified as a critical regulator of the mesenchymal identity of pancreatic carcinoma progenitor cells." (PMID 41148809, 2025). "Mechanistic exploration revealed a novel regulatory axis involving lncRNA FOXD1-AS1, miR-570-3p, and SPP1 in pancreatic cancer CSCs." (PMID 38167126, 2024). "Our study establishes that lncRNA FOXD1-AS1 up-regulates SPP1 expression by acting as a ceRNA that sponges miR-570-3p in pancreatic cancer CSCs." (PMID 38167126, 2024). "Collectively, our findings indicate that the presence of SPP1 is essential for facilitating pancreatic cancer CSC development by lncRNA FOXD1-AS1." (PMID 38167126, 2024). "CAF-secreted OPN promotes cancer stemness via the secreted phosphoprotein 1(SPP1)–CD44 axis in pancreatic cancer." (PMID 37143134, 2023). "In pancreatic cancer, SPP1 was expressed in both cancer cells and TAMs, and hypoxia has been suggested to induce SPP1 expression." (PMID 37190178, 2023). "SPP1 is a sialic acid-rich chemokine-like glycoprotein that is overexpressed in a variety of cancers, including pancreatic cancer." (PMID 38235128, 2023).
pancreatic cancer (continued). "SLC7A11-positive macrophages were identified in lung, colon, ovarian, and pancreatic cancer patients, and these macrophages were mainly detected among SPP1 positive macrophage sub-clusters." (PMID 36470862, 2022). "Amidst the duct subpopulation markers, Spp1 and Anxa3 caught our eye due to their known roles in pancreatic cancer progression; however, their functions in normal pancreatic duct epithelium have not been fully explored." (PMID 34009124, 2021). "SPP1 is expressed in pancreatic ductal tissues and undifferentiated pancreatic precursors, as well as in pancreatic cancer." (PMID 31513574, 2019). "The data filtering narrowed the number of genes to a final list of four that had limited information on pancreatic cancer as well as immunosuppression: secreted phosphoprotein 1 (SPP1, osteopontin), granulin, trefoil factor 2 (TFF2), and neuromedin U (NMU)." (PMID 30533259, 2018). "Meta-analysis of 11 studies revealed that patients with pancreatic cancer have elevated serum levels of SPP1." (PMID 27175805, 2016). "Furthermore, our findings reveal that lncRNA FOXD1-AS1 enhances self-renewal and tumorigenesis in pancreatic cancer CSCs by up-regulating osteopontin/secreted phosphoprotein 1(SPP1) and acting as a ceRNA to sponge miR-570-3p in pancreatic cancer (PC) CSCs." (PMID 38167126, 2024). "In addition, studies have suggested the critical role of the SPP1 – CD44 axis between macrophages and glioma cancer cells and between cancer-associated fibroblasts and pancreatic cancer cells." (PMID 39691723, 2024). "It has been reported that anti-SPP1 autoantibody is detected in sera of breast and pancreas cancer." (PMID 36038839, 2022). "An orthotopic pancreatic cancer mouse model was established, and in vivo and in vitro experiments including flow cytometry, Western blot, co-immunoprecipitation (Co-IP), and in vivo ubiquitination assays were conducted to validate the immunoregulatory role of tumor-derived SPP1." (PMID 41731467, 2026). "Furthermore, CAFs can induce pancreatic cancer cell stemness through the SPP1/CD44 axis." (PMID 38445456, 2024). "Prolonged exposure of pancreatic cancer (PC) cells to CAF-derived media enhances stemness and notably upregulates OPN/SPP1 expression in PC cells." (PMID 39919692, 2025). "Subsequent experimental validation revealed that lncRNA FOXD1-AS1 has the potential to enhance the expression of Osteopontin (OPN), also known as secreted phosphoprotein 1 (SPP1), in pancreatic cancer CSCs among the identified candidate genes." (PMID 38167126, 2024). "We recently identified that CAF promoted the enrichment of the stemness population through osteopontin (OPN) or secreted phosphoprotein 1 (SPP1) and CD44-mediated cellular cross-talk in pancreatic cancer cells." (PMID 36550571, 2022). "In addition, WDR5 ablation effectively results in the downregulation of immune checkpoints (PD-1, PD-L1, and Spp1) and immunosuppressive cytokines (TGFβ and IL6) in pancreatic tumor microenvironments, leading to improved CD8+/CD4+ T-cell infiltration." (PMID 39201460, 2024).
rheumatoid arthritis (65 papers, 2010 to 2025). A chronic, systemic autoimmune disorder characterized by inflammation in the synovial membranes and articular surfaces. "Intriguingly, similar profiles have been observed in rheumatoid arthritis, where SPP1 production in response to extracellular calcium drives inflammation." (PMID 40047497, 2025). "SPP1+ macrophages upregulated rheumatoid arthritis-related pathways in metastases, indicating their potential involvement in late-stage disease and metastasis." (PMID 41246350, 2025). "In recent studies, SPP1 siRNA has been used to treat mice with rheumatoid arthritis, which resulted in a significant inhibition of synovial proliferation, leukocyte infiltration, and articular cartilage erosion." (PMID 41357134, 2025). "While rheumatoid arthritis is an auto-immune disease that is found to be a risk factor for cardiovascular diseases, AOM1 is an antibody for SPP1 (osteopontin), the same MOA as ASK8007." (PMID 36815023, 2023). "Comparative analyses between rheumatoid arthritis and COVID-19 samples revealed similar pro-inflammatory disease patterns regulated via SPP1 and S100A12, leading to activation of proinflammatory CD14+ monocytes and PD-L1+ neutrophils." (PMID 35681519, 2022). "We found that bronchoalveolar lavage fluid (BALF) macrophage clusters FCN1+ and FCN1+SPP1+ predominant in severe COVID-19 were transcriptionally related to synovial tissue macrophage (STM) clusters CD48hiS100A12+ and CD48+SPP1+ that drive rheumatoid arthritis (RA) synovitis." (PMID 34143756, 2021). "SPP1 is upregulated in the serum and lungs of patients with systemic sclerosis (SSc), rheumatoid arthritis (RA), and dermatomyositis." (PMID 40559389, 2025). "In this study, we employed bioinformatics and machine learning techniques to identify seven key genes associated with rheumatoid arthritis (RA): AKR1B10, MMP13, FABP4, NCF1, SPP1, COL1A1, and RASGRP1." (PMID 39430588, 2024). "By performing intersection analysis on 35 cervical cancer prognosis related genes and RA differential genes, a total of 3 co-upregulated differential genes were identified, namely SPP1, LYZ, and MCM5, which were upregulated in patients with rheumatoid arthritis and cervical cancer." (PMID 41384115, 2025). "Moreover, genetic variants of SPP1 have been significantly linked to susceptibility and clinical severity in autoimmune diseases such as systemic lupus erythematosus (SLE) and rheumatoid arthritis (RA), underscoring its potential as a biomarker for irAEs." (PMID 41221294, 2025). "In the phases I and II clinical trials for rheumatoid arthritis, the drug ASK8007, a monoclonal antibody targeting SPP1, was investigated and presented no safety concern." (PMID 39456887, 2024).
Stroke (64 papers, 2010 to 2025). Sudden impairment of blood flow to a part of the brain due to occlusion or rupture of an artery to the brain. "Among these genes, such as Fabp5, Spp1, and Arg1, has been found in stroke-associated macrophages, foamy macrophages in atherosclerotic plaques, and lipid-associated macrophages in myocardial infarct." (PMID 40777042, 2025). "The knockout of the osteopontin gene (Spp1) reduces neuronal loss in a stroke model, consistent with osteopontin opsonising stressed/damaged neurons." (PMID 34948237, 2021). "In contrast, at 4 and 8 weeks after stroke, the expression of Cd44, Spp1, and Cd74 (encoding CD44, Spp1, and CD74, respectively) was increased." (PMID 31888302, 2019). "After stroke, SPP1+ MG caused pontine infarction axonal demyelination." (PMID 38988493, 2024). "Osteopontin (OPN), encoded by Spp1, is a cytokine‐like glycoprotein that binds to integrins and CD44 and is upregulated in stroke, CNS injury, and neurodegeneration." (PMID 40799188, 2025). "In contrast, Spp1 expression is upregulated at later stages of IS and will last for 2 weeks, suggesting a role for Spp1 in neurorestorative functions during the subsequent recovery phase following stroke." (PMID 40292254, 2025). "In animal models of stroke and spinal cord injury, Spp1 has been shown to promote angiogenesis and improve nerve function." (PMID 39939834, 2025). "The box plot illustrates that in the stroke group, the expression levels of Spp1 and Cav1 were significantly elevated, whereas the expression level of Per2 was reduced." (PMID 40292254, 2025). "This study identifies SPP1 signaling as a novel therapeutic target for post‐stroke neuropsychiatric sequelae." (PMID 41345421, 2025). "In another example of neuroprotection, regulatory T-cells localized in the brain several weeks after stroke express SPP1/OPN and, through a microglial-β1-integrin-dependent manner, foster repair of white matter axonal damage." (PMID 38646526, 2024). "Microglia and macrophage-derived Spp1 was predicted to signal back to both myeloid subsets, as well as stroke-specific OPCs (OPC_1) and stroke reactive astrocytes (AC_3 and AC_4) via Cd44." (PMID 39043661, 2024). "Relative information flow graph further demonstrated that SPP1 signaling pathway was the second most significantly upregulated pathways in the post-stroke Nhe1 cKO white matter tissues compared to those in the WT." (PMID 38509618, 2024). "Thanks to this method, a NVU transcriptome database was constructed, and it was possible to demonstrate that an osteopontin gene (Spp1) is upregulated after stroke." (PMID 38247841, 2024). "Genes linked to microglial responses to demyelination, Alzheimer’s disease, and stroke, including Apoe, Lpl, Spp1, Clec7a, and Cst7, are also upregulated." (PMID 39633897, 2024). "A recent study highlighted SPP1 as a central mediator of monocyte-to-endothelial signaling in thrombosis, and elevated osteopontin is a strong predictor of poor outcome in stroke, myocardial infarction and DVT." (PMID 37753073, 2023). "In murine stroke model, brain Tregs secrete osteopontin (SPP1) to promote tissue-regenerative microglial reactions for brain repair through the Integrin beta-1 (ITGB1) receptor, expressed on microglia." (PMID 35844606, 2022). "Moreover, Spp1 -> Cd44 signalling events from myeloid cells to stroke specific OPCs, reactive astrocytes and myeloid cells themselves ranged among the most robustly predicted interactions within our CCC analysis." (PMID 39043661, 2024). "In addition, the marker genes of Cd11c microglial cells are highly expressed, including Spp1, Cst7, Csf1, and Lpl, which are microglial cells related to neurodegenerative diseases and stroke injuries." (PMID 37577391, 2023). "The most significantly upregulated genes, including Lpl, Spp1, Cd36, Mmp2, and Mmp19, and the most highly enriched genes, including Cd5l, Mmp3, Mmp12, and Mmp13, indicate a pronounced disturbance in lipid homeostasis in infarcts at 7 weeks after stroke." (PMID 34819339, 2022).
Stroke (continued). "At 8 weeks post-stroke, the top 10 genes were Cd44 (degree = 14), Fcgr2b (degree = 13), C1qb (degree = 13), Cd74 (degree = 12), C1qc (degree = 11), Cd14 (degree = 10), C4a (degree = 10), Spp1 (degree = 10), RT1-A2 (degree = 9), and Itgb2 (degree = 9)." (PMID 31888302, 2019). "However, Spp1 is notably upregulated in pathological conditions, including neurodegenerative diseases such as Alzheimer's disease, Parkinson's disease, and multiple sclerosis, as well as acute brain injuries like stroke and hypoxic–ischemic injury." (PMID 39939834, 2025). "The CH25H+ microglia (MG6) express several neurotrophic factors, including Spp1, Gpnmb, and Lgals3, which was previously suggested to induce axon outgrowth and establish functional synapses, thus may contribute to neurogenesis after stroke." (PMID 37183260, 2023). "Our study identified astrocyte-specific differential expression of SPP1 and ANGPTL4, highlighting their crucial role in post-stroke angiogenesis." (PMID 40988927, 2025). "In a rat stroke model, post-injury administration of the ECM molecule osteopontin (SPP1) protected against BBB disruption, improved neurobehavior and stimulated autophagy in neurons." (PMID 36547263, 2023). "Targeting chemotactic signaling has been a trend in stroke intervention, as we observed in our experiments that upregulated OPN/SPP1 signaling, while inhibition of OPN reduces neuroinflammation and improves neurological function." (PMID 38071333, 2023). "At 4 weeks post-stroke, the top 10 gene products in the PPI network were Cd44 (degree = 17), C1qb (degree = 15), Fcgr2b (degree = 14), Spp1 (degree = 12), Cd74 (degree = 12), C4a (degree = 12), C1qa (degree = 12), C3 (degree = 10), Cd14 (degree = 10), and Itgb2 (degree = 10)." (PMID 31888302, 2019).